IL33 (interleukin 33)
Diseases named in the same sentence as IL33 in open-access papers (continued):
Sharing a sentence is not in itself a finding about the gene and the disease.
tumor (continued). "In conclusion, based on the in vitro study, IL-6 hasno significant effect on cell proliferation and invasion, but could exert pro-apoptosis effect and up-regulate tumor derived IL-33 and VEGF-A." (PMID 29100435, 2017). "Of note, IL-33 blockade efficiently alleviated tumor growth of untreated NSCLC xenografts." (PMID 28978138, 2017). "IL-33 blockade dramatically reduced FoxP3 expression in NSCLC tumor tissues." (PMID 28978138, 2017). "IL-33 can be detected not only in the tumor environment, but also in the serum of cancer patients." (PMID 28758974, 2017). "Next we examined if epithelial-cell derived IL-33 contributes to tumor development." (PMID 28710436, 2017). "Moreover, the window period of IL-33 expression in serum is longer and more stable than that in tumor tissue." (PMID 28402273, 2017). "Similarly, Panc02 tumours grown in Il33−/− mice contained a significantly less number of TAMs as compared with those tumours grown in wt mice as measured by immunohistochemistry and FACS." (PMID 27150562, 2016). "As IL-33 mainly acts as an amplifier of inflammation, targeting IL-33 may suppress the pro-tumorigenic inflammation in the tumor stroma, therefore improving the treatment with conventional therapies." (PMID 28119694, 2016). "As such, tumour-derived sST2 may interfere with IL-33-induced Th1 and Th2 responses in our model, which in turn may contribute to the anti-growth and anti-metastatic effects of sST2 in immunocompetent mice." (PMID 27882929, 2016). "Finally, IL-33 expression positively correlated with VEGF score in tumor cells in WT mice (r = 0.512; p = 0.018)." (PMID 26919112, 2016). "Similarly, PDGF-BB-expressing LLC tumours grown in Il33−/− mice also showed significantly decreased infiltration of TAMs that reached to a similar level of vector tumour grown in wt mice." (PMID 27150562, 2016). "To investigate the physiological meaning of the small but consistent enhancement of programmed oncosis in P29 cells by IL-33 under nutrient-depleted conditions, we subcutaneously injected P29 cells and A11 cells into B6 and IL-33−/− mice, and monitored tumour growth." (PMID 26775708, 2016). "Thus, the MHC-I and IL-33 co-relationship introduces a novel mechanism of cancer immune escape during tumour development, revealing the involvement of IL-33 into cancerogenesis." (PMID 27619158, 2016). "Although sST2-Fc seems to be weaker in suppressing the malignant growth of CRC cells than tumour cell-derived native sST2, it may be due to its lower affinity to IL-33 or a shortage of local accumulation of the protein in the tumour tissues." (PMID 27882929, 2016). "From these reports, we reasoned that tumour-derived sST2 could modulate the inflammatory tumour microenvironment through interference with IL-33-induced NF-κB signalling." (PMID 27882929, 2016). "Thus, it is likely that extracellular IL-33 in tumour tissues stimulates macrophage infiltration of the tumour stroma, and sST2 interferes with this process." (PMID 27882929, 2016). "Surprisingly, the analysis of IL-33 expression in cultured Panc02 cells in vitro showed only a modest expression level (<500 pg ml−1), although this level was higher than other cultured tumour cells." (PMID 27150562, 2016). "Yet, IL-33 may also trigger death of ST2-expressing lung tumor cells under conditions mimicking the tumor environment in vitro, including upon nutrient depletion or under hypoxic/anoxic conditions." (PMID 28119694, 2016). "Thus, IL-33 has a significant role in cancer immune-surveillance against primary tumours, which is lost during the metastatic transition that actuates immune escape in cancer." (PMID 27619158, 2016). "Our data demonstrated that IL-33 was abundantly expressed in P29 tumour tissues." (PMID 26775708, 2016). "It is plausible that systemic delivery of IL-33 protein in mice as shown in that study could elicit a broad immune response that favour tumour growth." (PMID 27150562, 2016).
tumor (continued). "IL-33-induced migratory effect could be important for the recruitment of TAMs in tumours from peripheral tissues such as those in surrounding tissues and peripheral blood." (PMID 27150562, 2016). "Furthermore, NG2+ pericytes in PDGF-BB tumours produced high levels of IL-33 as compared with those isolated from the vector control tumours." (PMID 27150562, 2016). "However, it was reported that transfection of IL-33 in tumor cells attenuated development of metastasis in B16 melanoma and in Lewis lung carcinoma metastatic models in mice." (PMID 26919112, 2016). "Additionally, expression of IL-33 is increased in the sera and tumor tissues of GC patients, and this increase correlates with depth of invasion, distant metastasis, advanced tumor stage, and poor survival." (PMID 27074834, 2016). "Taken together, these results suggest that sST2 may inhibit IL-33-induced monocyte infiltration and M2a polarization of the infiltrated cells, thereby reducing the stimulatory effects of TAMs on tumour angiogenesis, invasion and metastasis." (PMID 27882929, 2016). "If these cells do express functional ST2L, then IL-33 in the tumour microenvironment might directly affect their behaviour." (PMID 26775708, 2016). "Thus, sST2 seemed to inhibit both Th1 and Th2 responses induced by IL-33 in the tumour microenvironment." (PMID 27882929, 2016). "Both IL-1β and IL-33 were abundantly present in P29 tumours." (PMID 26775708, 2016). "Although the mechanisms by which IL-33/ST2 signaling may contribute to HCC are still elusive, tumor-infiltrating, IL-33-producing effector-memory CD8+ T cells have been observed in resected HCC tissue, which are associated with prolonged patient survival." (PMID 28119694, 2016). "However, PDGF-BB tumour-bearing Il33−/− mice showed attenuated metastasis as compared with PDGF-BB tumour-bearing wt mice." (PMID 27150562, 2016). "We found that expression of IL-33 significantly inhibited metastatic A9 tumour formation." (PMID 27619158, 2016). "The percentage of circulating tumour cells (CTC) that could be detected in distal organs was significantly lower in IL-33-expressing tumours." (PMID 27619158, 2016). "Interestingly, a significantly higher number of CTCs were found in IL-33-tumour-bearing mice as compared with vector tumour-bearing mice." (PMID 27150562, 2016). "Thus, both VEGF and IL-33 are substantially involved in and probably cooperate closely in inducing tumour angiogenesis in CRC." (PMID 27882929, 2016). "The opposite effect, however, has been obtained after inhibition of IL-33 in primary tumour cells." (PMID 27619158, 2016). "Indeed, immunostaining for IL-33 showed the presence of scattered positive cells in P29 tumours in both B6 and IL-33−/− mice." (PMID 26775708, 2016). "Why IL-33-positive cells exist in scattered cells in P29 tumours is presently unknown, but may be due to local concentrations of such IL-33-inducing factors." (PMID 26775708, 2016). "Expectedly, clodronate effectively ablated TAM numbers in both vector and IL-33-tumours." (PMID 27150562, 2016). "Interestingly, P29 tumours in B6 mice had more haemorrhagic necrosis in the centre of the tumour mass compared with the tumours in IL-33−/− mice." (PMID 26775708, 2016). "Comparing sensitivity and specificity of some tumor markers, we suppose that elevated serum IL-33 and IL-31 levels, especially IL-33, may relate to the process of EC and could be useful biomarkers for the diagnosis of that disease." (PMID 27340318, 2016). "However, exogenous IL-33 treatment enhanced DC maturation by the up-regulation of several costimulatory molecules, consistent with other studies in the non-tumor-bearing settings." (PMID 27517629, 2016). "Because we detected only one major processed band (approximately 18 kDa) in mouse CRC tumours, full-length IL-33 may be processed by elastase, thereby making the tumour microenvironment more inflammatory and enhancing CRC growth and metastasis." (PMID 27882929, 2016).
tumor (continued). "Although TAMs might affect several steps of the metastatic cascade, the IL-33-stimulated TAMs are likely to increase intravasation of tumour cells into the circulation." (PMID 27150562, 2016). "Interestingly, we found that TAMs were small in number in sST2 high-expressing tumours, suggesting that sST2 inhibited the IL-33-induced recruitment of monocytes or the attraction of marginal macrophages into tumour tissues." (PMID 27882929, 2016). "However, IL-33 can be detected not only in the tumor environment, but also in the serum of cancer patients." (PMID 28119694, 2016). "Furthermore, we discuss the major issues which we believe should be investigated in the future to improve our understanding of the role of IL-33 for tumor initiation/progression, toward the development of therapeutic strategies." (PMID 28119694, 2016). "Finally, in in vivo tumour models, we show that IL-33-activated TAMs mediate PDGF-BB-induced cancer metastasis." (PMID 27150562, 2016). "However, FACS analysis showed that the number of F4/80+ TAMs in IL-33-tumours was markedly increased as compared with that of vector control tumours." (PMID 27150562, 2016). "However, co-implantation of IL-33 tumour cells and macrophages resulted in massive tumour cell dissemination from the primary sites and distal metastasis." (PMID 27150562, 2016). "Because angiogenesis was suppressed in sST2 high-expressing tumours, IL-33 might be an important proangiogenic factor in CRC." (PMID 27882929, 2016). "Importantly, in several human and mouse graft tumour models, we provide compelling evidence to demonstrate that pericyte- and stromal cell-derived IL-33-activated TAMs are crucial for cancer metastasis." (PMID 27150562, 2016). "We next analysed circulating tumour cells (CTCs) in IL-33 and vector tumour-bearing mice." (PMID 27150562, 2016). "The next question is what IL-33-stimulated TAMs do for tumour growth and invasion." (PMID 27150562, 2016). "Thus, patients with low IL-33 expression had a shorter median time of survival (52.04 months), compared to patients with higher tumour IL-33 expression (80.62 months)." (PMID 27619158, 2016). "Interestingly, the mean expression of IL-33 in adjacent tissues to tumor was 64.1%, which was also significantly higher than in normal breast tissues from the same patients (p = 0.0002)." (PMID 24778632, 2014). "IL-33 has been found to enhance the activity of CD8+ T cells, NK cells and other tumor killer cells, therefore IL-33 may also have a role in tumor immunity or immunotherapy." (PMID 24959294, 2014). "IL-33 may also regulate the functional status of macrophages, which may regulate infectious and tumor immunity." (PMID 24959294, 2014). "IL-33 may also play a potential role in sustaining tumor growth, by modulating host immune responses against tumor cells and/or in the recruitment of SEMFs to support their growth." (PMID 23062310, 2012). "From this point of view, IL-33 may represent one of the effective weapons tumor cells utilize in order to create an ideal environment for obtaining optimal growth conditions." (PMID 23062310, 2012). "In addition, based on IL-33's ability to shift host immune responses to a Th2 phenotype, downregulation of tumor-specific immune responses can occur by inhibiting tumor antigen presentation." (PMID 23062310, 2012). "Therefore, IL-33 appeared to be a general nuclear marker of the endothelium expressed in both normal and tumor tissues." (PMID 18836528, 2008). "Moreover, abundant expression of IL-33 was also observed in the nucleus of endothelial cells in several distinct human tumors, indicating that IL-33 is a marker of tumor blood vessels as well." (PMID 18836528, 2008). "DAC/IL-33 and PD-1 mAb strongly synergized to increase tumor-infiltrating immune effector cells (i.e., CD4 T cells, CD8 T cells and eosinophils) and intratumoral expression of effector molecules (i.e., IFN-γ, granzyme B, perforin and TNF-α) which may account for therapeutic efficacy." (PMID 40317004, 2025).
tumor (continued). "Additionally, IL-33 may indirectly influence IL-17A activity by modulating regulatory T cells (Tregs), thereby contributing to a suppressive tumor immune landscape." (PMID 40725273, 2025). "Recent studies demonstrate that CAR-T cells armored with Superkine IL-2 and IL-33 can remodel the tumor microenvironment, enhance antitumor immunity, and suppress the growth of multiple solid tumors, with evidence suggesting that this combination may also mitigate antigen-loss–driven resistance." (PMID 41584600, 2025). "Thus, we speculate that the increased expression of IL-33 in tumor cells may contribute to abnormal DDR through transcriptional regulation of HR genes and IL-33/ST2/MAPK-mediated NHEJ activation." (PMID 40216748, 2025). "It is possible to speculate that HO induce basal release of TNF-α from MCs via an IL-33-independent mechanism, while, in tumor conditions, the IL-33 present in the co-culture can induce a greater release of TNF-α which may be responsible for the effects observed on TO." (PMID 40372523, 2025). "In addition, the extensive tumor cell death caused by anti-tumor drugs leads to the release of various danger-associated molecular patterns (DAMPs), many of which act as immunosuppressive mediators, such as HMGB1 and IL-33." (PMID 39994810, 2025). "IL-33 activates two pro-inflammatory factors, secreted IL-6 and IL-23, which lead to the expansion of Th17 cells and imbalance of Th17/Treg cells, ultimately leading to immune dysregulation, promoting the progression of inflammation and also promoting tumor growth in the tumor environment." (PMID 39925809, 2025). "Moreover, a negative correlation was detected between IL-33 and neutrophil count point, indicating that elevated IL-33 may suppress neutrophil-mediated anti-tumor immune response." (PMID 40943444, 2025). "The interplay between IL-31, IL-33, eosinophils, and the tumor microenvironment (TME) could significantly influence immunotherapy outcomes in NSCLC, and understanding these mechanisms is crucial for enhancing therapeutic efficacy and overcoming treatment resistance." (PMID 40305195, 2025). "However, the application of IL‐33 in tumor therapy is still in the research stage." (PMID 40860436, 2025). "Next, we evaluated whether IL-33 from tumor cells could affect the efficacy of chemotherapy." (PMID 40216748, 2025). "Therefore, we hypothesized that tumor-derived IL-33 and IL-18 might influence ILC2 frequency and function in PCa." (PMID 40247153, 2025). "In addition, SUMOylated nuclear IL-33 can promote the production of interleukin 8 (IL-8), which stimulates the IL-8 signaling pathway in macrophages, thereby promoting the migration and polarization of macrophages to the tumor-permissible phenotype." (PMID 40271196, 2025). "Therefore, chronic IL-33 signalling may upregulate tumour and stromal PD-L1 expression, promoting adaptive immune resistance." (PMID 41284319, 2025). "Thus, IL-33 and IL-13 may not only contribute to inflammation but also create a conducive environment for tumor progression by inhibiting antitumor responses." (PMID 40761291, 2025). "Furthermore, chemotherapy-naïve patients had elevated IL-33 expression, which decreased following neoadjuvant chemotherapy, suggesting that chemotherapy might reduce tumor aggressiveness by suppressing IL-33." (PMID 39125732, 2024). "Therefore, IL-33 might accelerate MF progression via a paracrine action in the tumor microenvironment, like in patients with myeloproliferative syndromes." (PMID 38607023, 2024). "Furthermore, IL-33 has been implicated in promoting the accumulation and maintenance of ST2+ Treg cells in inflamed tissues, exacerbating immunosuppression and facilitating tumor progression." (PMID 40236667, 2024). "In addition, Treg-intrinsic IL-33 is essential for Treg stability to evade anti-tumor immunity." (PMID 38825642, 2024). "However, the anti-tumor function of IL-33 in the context of LM remains to be studied." (PMID 38755133, 2024).
tumor (continued). "However, it is crucial to note that conflicting reports are suggesting that, in specific tumor microenvironments, IL-33/ST2 signaling may hinder NK cell activation." (PMID 40236667, 2024). "Besides, recent research has also highlighted the interplay between tumor-infiltrating Th2 cells and tumor cells, where tumor fungal elements activate signaling pathways in cancer cells, promoting the secretion of IL-33, which is essential for the recruitment and activation of Th2 cells." (PMID 38840908, 2024). "Down regulation of PCAT-1 can induce T cell recruitment and activate IL-13/IL-33 mediated pathway, inhibit tumor metastasis caused by CAF mediated activation of stromal fibroblasts, enhance the sensitivity of tumor cells to chemotherapy drugs and affect the microenvironment of tumor immune cells." (PMID 39705424, 2024). "In addition, IL-33 can act directly on tumour cells to enhance chemoresistance." (PMID 38662248, 2024). "Consequently, the activity of IL-33 could be envisioned as an amplifier of the pre-existing immune response within the tumor microenvironment." (PMID 38881897, 2024). "Molecules such as Il-33′s activity may be one of the major reasons for tumor immune tolerance." (PMID 36836154, 2023). "Moreover, AREG mAbs and IL-33 concertedly inhibited tumor growth." (PMID 37611111, 2023). "However, during the transition of polyps to adenocarcinoma, a different subset characteristic of connective tissue MC expands and accumulates inside the tumor stroma in an IL-33-dependent manner, supporting cancer’s ability to change the MC activity toward a pro-cancer function." (PMID 36766801, 2023). "Thus, IL-33 may be a promising novel cytokine for tumor immunotherapy through its promotion of cancer-eradicating T cell immune responses." (PMID 37056569, 2023). "Therefore, the correlation between IL-33 expression and the prognosis of tumor patients may exceed our calculation." (PMID 37507682, 2023). "Also, IL-33 can restrict tumor growth and metastasis through eosinophils." (PMID 37153553, 2023). "Interestingly, several human studies indicate that endogenous IL-33 might function as an antitumor agent, with its absence in tumor tissue potentially fostering metastasis." (PMID 37762328, 2023). "However, IL-33 also promotes tumor development and angiogenesis by various mechanisms." (PMID 36246629, 2022). "However, other studies have shown that IL33 promotes tumor development." (PMID 36567723, 2022). "Besides, IL-33 induced a direct tumor-killing effect by enhancing the expression of effector molecules, including degranulation markers (CD63 and CD107a), activators (CD69), adhesion molecules (CD11b/CD18 and ICAM-1), cytokines (TNF-α), and effector molecules (granzyme A)." (PMID 36291105, 2022). "In a mouse model of GC, mast cells were proved to be the major effector cells of IL-33 and could promote GC by recruiting macrophages; the frequencies of ILC2s and Tregs were comparable between tumor and normal tissues regardless of ST2 deficiency in mice." (PMID 35720302, 2022). "Overexpression of IL-33 in Apcmin/+ mice increased tumour burden and correlated with an increase in colonic ST2+ Tregs, while our group showed that IL-33-deficiency reduced tumour Tregs in Apc1322T/+ mice, although these studies did not directly assess the functional importance of Tregs." (PMID 36263033, 2022). "However, the specific role of IL-33/ST2 axis that might predominate in tumor remains to be further studied." (PMID 35634336, 2022). "Interestingly, in GC patients, the transcriptional signature of activated MCs with IL-33 and TAMs’ markers correlates with decreased patient survival, suggesting that IL-33 is a potent tumor-derived molecule capable of activating MCs to foster their pro-tumorigenic role in GC." (PMID 35159157, 2022).